APOA1 (apolipoprotein A1)
Diseases named in the same sentence as APOA1 in open-access papers (continued):
Sharing a sentence is not in itself a finding about the gene and the disease.
aortic valve calcification (1 paper, 2025). "A high APOB/APOA1 suggests that the balance between “promotion” and “inhibition” is disrupted, which may explain the increased risk of aortic valve calcification with an elevated APOB/APOA1." (PMID 40787622, 2025). "The lipid parameters APOA1, APOB/APOA1, cumulative LDL exposure, and non-HDL/HDL have been demonstrated to be associated with aortic valve calcification." (PMID 40787622, 2025).
aplastic anemia (1 paper, 2022). Anemia resulting from bone marrow failure (aplastic or hypoplastic bone marrow). "This antibody was successfully used to verify ApoA1’s role as a biomarker of aplastic anemia by selectively immunodepleting this protein from patient serum." (PMID 35840315, 2022).
artery occlusion (1 paper, 2020). "Age (OR 1.022; 95%CI, 1.007 to 1.036) was an independent risk factor for single artery progressed to multiple artery occlusion, while ApoA1 (OR 0.453; 95% CI, 0.235 to 0.953) was a protective factor." (PMID 32103113, 2020).
Ascites (1 paper, 2011). Accumulation of fluid in the peritoneal cavity (between the layers of the peritoneum that lines the abdomen). "There were eight proven false negatives of FT: 5 due to low A2M (large ascites or severe undernutrition), and three due to high ApoA1." (PMID 21492460, 2011).
astrocytomas (1 paper, 2019). "Studies showed that Serum Albumin (ALBU) and Apolipoprotein A-I (APOA1) proteins were up-regulated in grade III astrocytomas, facilitating tumor proliferation through an increase in neovascularization and migration of tumor cells." (PMID 31357616, 2019).
bacterial meningitis (1 paper, 2017). Inflammation of the membranes surrounding the brain and spinal cord due to a bacterial infection. "The authors propose an algorithm to predict bacterial meningitis based on elevated apolipoprotein A1, also found to be elevated in bacterial meningitis by Song and colleagues, and complement C3, which participates in clearance of encapsulated microbes and in clearance of neuronal synapses." (PMID 28670576, 2017).
bladder (1 paper, 2021). "Indeed, the exact mechanism of apolipoprotein A1 function in bladder carcinogenesis is yet to be clarified." (PMID 34947825, 2021).
bladder tumors (1 paper, 2021). "When the patients were stratified as cohorts with respect to the different bladder tumor pathologies, combined genotypes of APOA1 −75 and GA + AA (75.0%) were associated with high grade bladder tumors, conferring a three-fold increased risk (p = 0.04)." (PMID 34440141, 2021). "The frequency of the variant genotype APOA1 −75 AA was observed to be higher in the cases than in the controls (18.5 % vs. 6%, respectively), and conferred a 3.7-fold risk to bladder tumor development (p = 0.001)." (PMID 34440141, 2021). "Bladder tumor cases were significantly associated with the APOA1 −75 AA genotype (p < 0.05), while the APOA1 +83 C/T heterozygotes showed an association with cases (p < 0.05)." (PMID 34440141, 2021). "Bladder tumor cases that carried the variant genotype APOA1 −75AA were found more (70.0%) with a higher expression (≥20 ng/mL)of the APOA1 urinary protein and differed significantly against wild type GG (p = 0.03)." (PMID 34440141, 2021). "Furthermore, the APOA1 protein expression was concluded to have a possible role as a diagnostic marker for different grades of malignant bladder tumors." (PMID 34440141, 2021). "The current finding depicts that APOA1 −75 G/A and its protein expression could act as a promising marker risk assessment and for the development of bladder tumors." (PMID 34440141, 2021). "Likewise, the frequency of the APOA1 −75 variant A allele was found to confer a significant risk for bladder tumors compared with the controls (3.1% vs.26%, respectively; p = 0.004)." (PMID 34440141, 2021). "The APOA1 +83 C/T SNP showed an inverse relation with respect to the risk of bladder tumor." (PMID 34440141, 2021). "The APOA1 combined haplotypic effect confers a significant risk for bladder tumors." (PMID 34440141, 2021). "Finally, our results show variant −75 G/A, with the AA genotype, was significantly associated, with a nearly four-fold risk for bladder tumor in addition to its significant relation with APOA1 urinary expression." (PMID 34440141, 2021). "The results in our report seem to indicate that APOA1 −75 G/A and +83 C/T could markers for risk assessment in bladder tumor, as the results from the individual studies from different regions have come up with similar findings in different diseases, including cancer." (PMID 34440141, 2021). "This shows that the overall APOA1 concentration and its genotypes have an individual significance with respect to bladder tumors, other than its characteristics." (PMID 34440141, 2021). "Once the calibration curves were proven to be analytically optimal, APOA1 was measured in the urine samples of the bladder tumor patients using ELISA, according to the manufacturer’s protocol." (PMID 34440141, 2021). "It is clear that APOA1 derangement at a genetic level is mainly involved in late stage bladder tumors." (PMID 34440141, 2021). "Again, in low grade bladder tumors, urinary APOA1 protein was exhibited significantly more (52.4% vs. 15.4% high grade) with a higher expression (≥20 ng), while high grade tumor cases (84.6% vs. 47.5% low grade) showed a lower APOA1 expression (<20 ng/mL) (O.R = 6.08, p = 0.002)." (PMID 34440141, 2021). "In this study, the APOA1 protein levels were measured and a classification was done according to the optimal cutoff values, which were taken as a measure of the mean in the control urine samples (18.22 ng/mL) and in the bladder tumor cases (20 ng/mL)." (PMID 34440141, 2021). "The fact that a marked reduction in APOA1 levels occur during inflammation corroborates well with our findings, where we found a definite correlation between a lower expression of APOA1 with higher bladder tumor grades and stages." (PMID 34440141, 2021).
cardiac hypertrophy (1 paper, 2021). "cardiac hypertrophy, cancer, cell death and survival with upregulation of proteins such as MYH7, MYL2, APOA1 and phospholamban (Table of Top enriched networks from core analysis of both H9c2 and GK overexpressed proteins S1 Table)." (PMID 34166385, 2021).
cerebral malaria (1 paper, 2016). A sequestration of Plasmodium falciparum in the brain, which can cause coma and/or seizures. "The incidence of ECM was not significantly decreased in the ApoA1−/− mice compared to the WT mice, suggesting that the decreased level of HDL cholesterol is not responsible for the protection against cerebral malaria observed in the ApoE−/− mice." (PMID 27647324, 2016).
cervical adenocarcinoma (1 paper, 2020). An adenocarcinoma arising from the cervical epithelium. "We suggest that APOA1 may be a novel candidate marker for cervical adenocarcinoma and further study is needed to determine its functional mechanisms." (PMID 33194326, 2020). "We performed proteomics analysis on samples of cervical adenocarcinoma mucus and normal cervical mucus a nd used functional annotation to screen out differently expressed proteins relevant to immune, metabolic, cell adhesion, and other cellular processes, such as myeloperoxidase and APOA1." (PMID 33194326, 2020).
chlamydial infection (1 paper, 2019). "Interestingly, during chlamydial infection, ABCA1, CLA1, and ApoA-1 localize to the inclusion membrane and both CLA1 and ApoA-1 are found in discrete foci within the inclusion lumen." (PMID 31649655, 2019).
chronic pancreatitis (1 paper, 2011). A chronic inflammatory process causing damage and fibrosis of the pancreatic parenchyma. "Of these, 118 (36%) were proven false positives of FT, due to 1) low haptoglobin in 114 (mostly hemolysis); 2) high GGT in two (chronic pancreatitis); and 3) low ApoA1 in two (severe undernutrition)." (PMID 21492460, 2011).
co-infection (1 paper, 2024). "The table presents measures of interaction between HPV and Fungi co-infection on cervical lesions, adjusted for age, pregnancy, parity, apolipoprotein A1, apolipoprotein B, total cholesterol, and triglyceride." (PMID 39257614, 2024).
colorectal polyps (1 paper, 2024). "The TC, TG, and ApoB/ApoA1 ratios were also linked to colorectal polyps, according to ROC curve analyses." (PMID 39252808, 2024). "The TC, ApoB and ApoB/ApoA1 ratios were also linked to colorectal polyps, according to ROC curve analyses." (PMID 39252808, 2024). "ROC curve analyses revealed that TC, ApoB, and ApoB/ApoA1 ratio were associated with colorectal polyps." (PMID 39252808, 2024).
Combined hyperlipidemia (1 paper, 2025). "In contrast, the ratio of essentially non-CM components CH and familial combined hyperlipidemia to ApoA1 is almost equal among both chambers." (PMID 40562102, 2025).
diabetic foot ulcers (1 paper, 2022). "Increasing age, smoking, retinopathy, eGFR and inflammatory biomarkers like low levels of ApoA1 (p < 0.005) and IL-10 (p < 0.001) significantly contributed to the development of diabetic foot ulcers." (PMID 35836916, 2022). "This study aims to find the association between ApoA1, IL-10, TNF-α and diabetic foot ulcers, and whether their levels can assess the severity of the disease." (PMID 35836916, 2022).
epilepsy (1 paper, 2020). A brain disorder characterized by episodes of abnormally increased neuronal discharge resulting in transient episodes of sensory or motor neurological dysfunction, or psychic dysfunction. "Apolipoprotein A1 (APOA1) was also found to be decreased in the plasma of patients with epilepsy." (PMID 33082886, 2020).
familial amyloid polyneuropathy (1 paper, 2022). "TTR amyloidosis is the most prevalent and well-characterized of the three major forms of familial amyloid polyneuropathy, the others being apolipoprotein A1-associated and gelsolin-associated amyloid neuropathy." (PMID 36341129, 2022).
familial hypertriglyceridemia (1 paper, 2023). "In rare cases, such as patients with familial hypertriglyceridemia, their HDL-C tends to be low, but ApoA1 is not necessarily low, and measuring ApoA1 and HDL-C simultaneously can help clinical diagnosis." (PMID 37711173, 2023).
gastritis (1 paper, 2022). Inflammation of the stomach. "We find these proteins in different subsets of our comparative analyses, e.g., APOA1 and AHSG in GC vs. U, and FGA in NGM vs. GC, but, with the exclusion of the shared proteins with the gastritis and U datasets, they are not significant anymore." (PMID 35566209, 2022).
Headache (1 paper, 2021). Cephalgia, or pain sensed in various parts of the head, not confined to the area of distribution of any nerve. "Finally, the expression intensity of APOA1 was confirmed to be strongly down-regulated (p < 0.001) in both migraineur groups compared to non-headache control women, and TTHY protein signals were up-regulated (p < 0.01) in the same comparisons, validating all previous results." (PMID 33923220, 2021).
hepatoblastoma (1 paper, 2014). Hepatoblastoma (HB) is a malignant hepatic tumor and is the most common pediatric liver cancer. "The expression of mRNA and protein of ApoA1 in Human HepG2 hepatoblastoma cells and subline HepG2.2.15 cells were performed by reverse transcription-polymerase chain reaction (RT-PCR) and Western-blot." (PMID 25115832, 2014).
Hernia (1 paper, 2018). "Apolipoproteins were analyzed with an immunoassay for multiplexed detection of APOA1, APOA2, APOB, APOC2, APOC3, and APOE, and all six proteins were found to be significantly elevated in urine samples of BC patients when compared to controls (hernia patient volunteers)." (PMID 30544619, 2018).
Hirsutism (1 paper, 2025). Abnormally increased hair growth referring to a male pattern of body hair (androgenic hair). "After adjusting for age and BMI, a significant linear relationship was observed between MAP and WC, WHR, hirsutism score, FBG, LDL, TG, TC, ApoB, and ApoB/ApoA1 ratio." (PMID 41040863, 2025).
hyperandrogenism (1 paper, 2022). Excessive secretion of androgens from the adrenal glands or gonads. "APOA1 was significantly reduced in PCOS patients independent of BMI or hyperandrogenism." (PMID 36072434, 2022).
Hyperbilirubinemia (1 paper, 2026). An increased amount of bilirubin in the blood. "Hyperbilirubinemia was also associated with lower TC, TG, LDL-C, and ApoB levels, as well as the ApoB/ApoA1 ratio." (PMID 41598393, 2026). "Hyperbilirubinemia was also negatively associated with TC (p < 0.0001), TGs (p < 0.0001), LDL-C (p = 0.0061), very LDL-C (VLDL-C; p = 0.0043), and apolipoprotein B (ApoB; p < 0.0001) levels, as well as the ApoB/apolipoprotein A1 (ApoA1) ratio (p = 0.0003)." (PMID 41598393, 2026). "Hyperbilirubinemia significantly reduced serum TC, TG, LDL-C, and ApoB levels, as well as the ApoB/ApoA1 ratio." (PMID 41598393, 2026). "The associations of hyperbilirubinemia with HDL-C (<1.0 mmol/L) and ApoA1 (<1.0 g/L) levels became nonsignificant after full adjustment." (PMID 41598393, 2026).
hypolipoproteinemia (1 paper, 2022). Conditions with abnormally low levels of lipoproteins in the blood. "In addition, decreased ApoA1 (mainly seen in HDL) and ApoB (mainly seen in VLDL and LDL) can be explained by the hypolipoproteinemia, related to decreased cholesterol and inflammatory stress in SCD(Yalcinkaya, Unal, Oztas 2019)." (PMID 36459297, 2022).
ischemic disease (1 paper, 2024). Lack of blood supply to an area of the body, resulting in impairment of tissue oxygenation. "In this study, we found from a genetic perspective that an increase in the ApoB/ApoA1 ratio is significantly associated with the occurrence of ischemic diseases, especially IHD, ischemic cerebrovascular disease, and PAD." (PMID 38310324, 2024).
juvenile idiopathic arthritis (1 paper, 2005). Juvenile idiopathic arthritis (JIA) is the term used to describe a group of inflammatory articular disorders of unknown cause that begin before the age of 16 and last over 6 weeks. "ApoA-1 is regarded as a 'negative' acute-phase protein and has been described as being present only in reduced levels in sera from patients with RA and juvenile idiopathic arthritis, which makes it an unlikely candidate for systemic counter-regulation of cytokine production in RA." (PMID 16277671, 2005).
leukopenia (1 paper, 2023). "After the administration of thiopurines, CH (p = 0.02), HDL (p = 0.01), ApoA1 (p = 0.01), and ApoB (p = 0.03) had higher levels in the leukopenia group compared to the non-leukopenia group." (PMID 37441519, 2023).
malignant glioma (1 paper, 2011). A grade III or grade IV glioma arising from the central nervous system. "In a recent review, up-regulation of serum albumin and apolipoprotein-A1 were commented as the consequence of the blood brain barrier degradation in malignant gliomas." (PMID 21470419, 2011).
mucinous tumors (1 paper, 2019). "Similarly, apolipoprotein A1 has been detected in conjunction with transthyretin and transferrin in low grade mucinous tumors." (PMID 31315664, 2019).
Mycoplasma infections (1 paper, 2025). "The diagnostic value of ApoA-1 in dogs with fever, APRs, and dogs with acute B. canis and hemotrophic Mycoplasma infections, respectively, seems questionable." (PMID 41437958, 2025). "This study aimed to assess the potential of ApoA-1, CRP, cholesterol, and triglycerides as potential biomarkers in dogs with acute B. canis and hemotrophic Mycoplasma infections to classify an APR." (PMID 41437958, 2025). "Similarly, no significant changes in ApoA-1 concentrations were detected in dogs with acute hemotrophic Mycoplasma infections, in dogs tested serologically positive for Babesia spp., and in clinically healthy dogs." (PMID 41437958, 2025).
oral squamous cell carcinoma (1 paper, 2024). "Another study using a lectin-based electrophoresis method demonstrated overexpression of mannose-glycosylated AAT and APOA1 were significantly upregulated in serum of oral squamous cell carcinoma (OSCC) patients." (PMID 38600440, 2024).
Osteopenia (1 paper, 2023). Osteopenia is a term to define bone density that is not normal but also not as low as osteoporosis. "It is speculated that APOA1, FBN1, NOTCH1, SYT7 and KLF10 played key roles in regulating bone metabolic balance and in reversible osteopenia after PAOO, which might be involved in the accelerated tooth movement." (PMID 38012627, 2023). "It is speculated that APOA1, FBN1, NOTCH1, SYT7 and KLF10 play key roles in regulating bone metabolic balance and in reversible osteopenia after PAOO, which might be involved in the accelerated tooth movement." (PMID 38012627, 2023).
overactive bladder syndrome (1 paper, 2021). "Moreover, urinary ketamine, norketamine and dehydronorketamine contents (measured via LC-SRM-MS) were found to be positively correlated with overactive bladder syndrome score (OABSS) and APOA1 levels with urinary RBC, WBC, OABSS and numeric pain rating scale in KA." (PMID 33953300, 2021).
parasitic infection (1 paper, 2020). "HDL-C and its major structural protein (apoA-1) directly exert anti-inflammatory effects by neutralizing lipopolysaccharides (LPS), thus playing an important role in host resistance to bacterial, viral, and parasitic infection." (PMID 33344516, 2020).
plague (1 paper, 2022). Plague is a severe bacterial infection caused by the gram-negative bacterium Yersinia pestis. "A cohort study shows that apoB/apoA1 ratio is an independent predictor for patients with atherosclerotic cardiovascular disease (ASCVD) who are attacked by plague rupture, erosion or thrombus." (PMID 36445669, 2022).
Pleural effusion (1 paper, 2025). The presence of an excessive amount of fluid in the pleural cavity. "Unlike the mitochondria-associated genes in pleural effusion, BL liver metastases had elevated apolipoprotein genes, such as APOC1, APOA1, and APOE." (PMID 39955556, 2025).
retinal diseases (1 paper, 2020). "A higher level of ApoB and a lower level of ApoA1 may contribute to the risk of RE-related retinal diseases." (PMID 33614678, 2020).
Schistosoma haematobium infection (1 paper, 2025). "A potential role of ApoA1 in Schistosoma haematobium infection could involve molecular mimicry, wherein the parasite exploits its immunomodulatory properties to evade detection by the host immune system." (PMID 40853910, 2025).
schistosomiasis (1 paper, 2025). An infectious disease caused by parasitic trematodes of the genus Schistosoma that colonize human blood vessels and release eggs that can cause granulomatous reactions leading to acute (swimmer's itch or acute schistosomiasis syndrome) or chronic disease. "ApoA1 interacts with LCAT, influencing lipid metabolism and immune responses during infection; thereby suggesting a complex interplay between lipoproteins and immune modulation in schistosomiasis." (PMID 40853910, 2025).
schwannoma (1 paper, 2024). A benign, usually encapsulated slow growing tumor composed of Schwann cells. "In contrast, conditioned media from schwannoma cells with CRISPRi suppression of APOA1 or the radiotherapy sensitivity hit KDM5C inhibited lymphocyte migration." (PMID 38216587, 2024). "Ontology analyses of 425 differentially expressed proteins from conditioned media revealed enrichment of apolipoproteins after ionizing radiation, and a parallel reaction monitoring targeted assay validated secretion of APOA1 and other chemokines from surviving schwannoma cells." (PMID 38216587, 2024).
temporal lobe epilepsy (1 paper, 2024). A localization-related (focal) form of epilepsy characterized by recurrent seizures that arise from foci within the temporal lobe, most commonly from its mesial aspect. "Several apolipoproteins (APOA1, APOD, and APOA4), serpin protease inhibitors (SERPINA3, SERPINF1, etc.), complement components (C9, C8, and C1R), and a total of 42 proteins were found to be significantly upregulated in the temporal lobe epilepsy group." (PMID 39063177, 2024).